IL6 (interleukin 6)
Diseases named in the same sentence as IL6 in open-access papers (continued):
Sharing a sentence is not in itself a finding about the gene and the disease.
Obesity (3,805 papers, 2001 to 2026). Accumulation of substantial excess body fat. "In RRMS, obesity is associated with elevated serum and CSF levels of pro-inflammatory cytokines such as IL-6 and adipokines, including leptin, resistin, and chemerin, alongside reduced levels of the anti-inflammatory adipokine adiponectin." (PMID 41562846, 2026). "Obesity is generally associated with elevated IL-6, IL-1β, and IFN-γ levels due to an increased M1 macrophage population and chronic low-grade inflammation." (PMID 41596532, 2026). "The evaluation of the obtained AUC values allowed to clearly highlight the superior discrimination performance of ACLI regarding the inflammatory markers hs-CRP and IL-6 in patients with overweight and obesity involved in dietary interventions for weight loss." (PMID 41899249, 2026). "Proinflammatory cytokines, including IL-6, have been implicated in the pathogenesis of the cardiac dysfunction associated with obesity cardiomyopathy." (PMID 41678287, 2026). "In our analysis of inflammatory cytokine levels, we found that CCPP intervention reduced the concentrations of pro-inflammatory factors (TNF-α, IL-1β, and IL-6) and alleviated inflammatory responses associated with obesity development." (PMID 41596915, 2026). "Cross-sectional and prospective assessment of the association of different measures of obesity (BMI, WC and %BF) and IL-6, CRP and adiponectin at 22 years of age, in a population-based Birth Cohort in Southern Brazil." (PMID 40717997, 2025). "In pre-clinical studies, IL-6 knockout mice developed obesity, associated with a disturbed carbohydrate and lipid metabolism." (PMID 41141350, 2025). "Obesity-related DN is closely associated with chronic, low-grade inflammation and cytokine expression (IL-1α, IL-6, TGFβ, and TNFα), leading to leukocyte recruitment and DN." (PMID 41369384, 2025). "Increased intrahepatic NF-κB is associated with obesity, hepatic steatosis, insulin resistance, and plasma levels of IL-6." (PMID 39928502, 2025). "IL6 is a key immunomodulatory cytokine mainly involved in regenerative processes including tendon repair, OA pathophysiology and is elevated in obesity-associated inflammation." (PMID 41150772, 2025). "CCL2 mediates monocyte recruitment, M1 polarization and the upregulation of TNF-α and IL-6 in fat pads, contributing to the inflammatory milieu linked to obesity-associated comorbidities." (PMID 40328980, 2025). "The primary source of elevated circulating IL-6 levels in obesity emanates from immune cells within adipose tissue, with heightened IL-6 release being closely linked to obesity." (PMID 40519917, 2025). "IL-6 trans-signaling is implicated in recruiting macrophages to adipose tissue in obesity, contributing to inflammation." (PMID 41277875, 2025). "In conclusion, this study highlights IL-6, Ca2+, sAA, and cortisol as a potential salivary biomarker-combination associated with obesity warranting further investigation." (PMID 41584074, 2025). "IL-6 has been linked mainly with insulin resistance and diabetes in obesity-derived chronic inflammation." (PMID 40430061, 2025). "Certain gene polymorphisms (eg, in TNF-α, IL-6, or muscle growth regulators such as myostatin) have been implicated in sarcopenia and obesity separately." (PMID 40718355, 2025). "Obesity is a chronic disease associated with systemic inflammation caused by excess visceral fat and pro-inflammatory cytokines such as IL-1β and IL-6." (PMID 41422827, 2025). "IL‐6, produced by various cells including adipose tissue, is also linked to obesity and insulin resistance." (PMID 40551726, 2025). "Obesity is associated with increasedsecretion of pro-inflammatory cytokines, thus we evaluated the expressionlevels of the inflammatory markers IL-6, TNF-α, and MCP-1 inboth subcutaneous and visceral fat tissues." (PMID 39895065, 2025).
Obesity (continued). "Low-grade inflammation is a hallmark of adult obesity, with adipose tissue depots producing and secreting inflammatory mediators, most frequently IL-6, interleukin-8 (IL-8), interleukin-1 receptor antagonist (IL-1Ra), and TNF-α, among others." (PMID 40426748, 2025). "In the context of obesity, IL-6 is intricately associated with chronic inflammatory processes and contributes to the inhibition of hepatic insulin signaling through the induction of SOCS3 protein expression." (PMID 40519917, 2025). "While studies in general populations demonstrate robust associations between obesity, elevated IL-6, and depressive symptoms, findings in schizophrenia are inconsistent." (PMID 40791199, 2025). "Obesity is linked to an increase in inflammatory cytokines, such as interleukin-6 (IL-6), IL-18, and tumor necrosis factor alpha (TNF-α), which are believed to play a role in HS and AC." (PMID 40969999, 2025). "Chronic IL-6 elevation, such as that observed in obesity or systemic inflammation, has been implicated in the development of insulin resistance." (PMID 41155560, 2025). "One commonly proposed mechanism of obesity-related immune dysfunction is the underlying chronic inflammatory state of obesity, with increased levels of inflammatory cytokines including TNFα, IL6, and leptin." (PMID 40386706, 2025). "The current analysis showed a significant association between chronic stress, higher IL-6 levels, and obesity, as the increase in stress levels was associated with 30 % higher odds of obesity, and 29–38 % of this was statistically explained by higher IL-6." (PMID 41019535, 2025). "Linked with immunological disorders.Diabetes: High blood sugar affects neutrophil activity and T cell responses, increasing the infection risk.Obesity causes low-grade inflammation from higher pro-inflammatory cytokines (IL-6, TNF-α)." (PMID 40364844, 2025). "Interleukin-6 (IL-6) is a key pro-inflammatory cytokine implicated in obesity, insulin resistance, and atherosclerosis, while leptin is an adipokine secreted by adipose tissue that bridges energy homeostasis with immune function." (PMID 41384023, 2025). "Myeloid cells respond to IL-6 through Jak/Stat3, which has been implicated in inflammatory disease and inflammation-promoted obesity-associated cancer." (PMID 40801626, 2025). "High IL-6 secretion by brown fat cells in mice causes the failure of brown fat cells to decompose fat or metabolize glucose and other substances, resulting in obesity and other related complications, supporting the present study." (PMID 40083433, 2025). "Chronic inflammation associated with obesity triggers the release of IL-6, which stimulates hepcidin production, leading to ID." (PMID 40298814, 2025). "Our study confirmed a positive association between IL-6 and obesity, and further showed significant associations between high IL-6 and features of metabolic syndrome like high blood pressure." (PMID 39714726, 2025). "In the general population, elevated IL-6 levels have frequently been linked to obesity and metabolic dysfunction." (PMID 41323348, 2025). "Concerning the role of IL-6 in aging and obesity, a positive and significant association between serum IL-6 and visceral fat mass has been shown in a small cohort of 77 patients aged ≥ 65 years old." (PMID 41227378, 2025). "The accumulation of cytosolic citrate increases the acetylation of a specific histone residue (H3K18), which was previously associated with elevated IL‐6 levels in individuals with obesity." (PMID 40265287, 2025). "This study underscores the significant association between IL-6, asthma, obesity, and metabolic dysfunction." (PMID 39714726, 2025). "In particular, along with the carcinoma cell per se, TAM represent an important cellular source of several pro-cancerous cytokines, i.e., IL-6, postulated to fuel obesity-associated breast tumorigenesis." (PMID 40868123, 2025).
Obesity (continued). "Overall, this systematic review suggests that weight loss reduces circulating IL‐6 in people with obesity across all life stages and a range of diseases." (PMID 40090867, 2025). "MCP-1 and TNF-α play crucial roles in the relatively early stages of inflammation associated with obesity, whereas IL-6 and IL-1β are potentially involved in the later phases of inflammation." (PMID 39803918, 2025). "Adipocytokines such as TNF-α, IL-6, and adiponectin play pivotal roles in mediating insulin resistance and linking obesity to increased cardiovascular risk." (PMID 41008514, 2025). "In analyses of IL-6, obesity versus healthy weight was associated with higher concentration (P-value<0.001)." (PMID 40920854, 2025). "This study underscores the significant association between elevated IL-6 levels and asthma, particularly in the context of obesity and metabolic dysfunction." (PMID 39714726, 2025). "Recent observational clinical data show that obesity-associated sarcopenia is accompanied by lower irisin and higher IL-6 levels, both of which correlate with reduced handgrip strength and muscle mass." (PMID 41515940, 2025). "Elevated IL-6 levels are commonly observed in obesity and have been linked to altered insulin sensitivity in hepatic tissue and pancreatic β-cells, thereby contributing to the development of insulin resistance." (PMID 40722699, 2025). "Circulating FABP4 promoted obesity-associated breast cancer by increasing mammary tumor stemness and aggressiveness through the IL-6/STAT3/ALDH1 axis." (PMID 41392988, 2025). "In this nested case–control study of Mediterranean individuals with overweight/obesity and MetS, higher baseline concentrations of IL-6, IL-1ra, TNFα, and IL-1β were associated with an increased risk of incident CKD after one-year follow-up." (PMID 40867871, 2025). "While ROC analysis demonstrates the diagnostic potential of IL-6 and other cytokines, it is critical to acknowledge that BMI remains the gold standard for obesity diagnosis due to its simplicity and clinical feasibility." (PMID 40519917, 2025). "Some inflammatory markers, such as C-reactive protein and interleukin-6, have been linked to deregulated neurohormonal circuits in both obesity and depression." (PMID 40292529, 2025). "One of the potential regulators that increases following the HFD is IL-6, a cytokine produced in response to inflammation associated with obesity and a HFD." (PMID 40741169, 2025). "Obesity is associated with increased levels of interleukin-6 (IL-6) and tumor necrosis factor-α (TNF-α)." (PMID 40909922, 2025). "Association studies have suggested a potential IL-6 role in elevated BP in obesity via angiotensin II, which needs to be confirmed by interventional studies." (PMID 40761303, 2025). "In subsequent analyses, we explored the extent to which genetically proxied IL-6 signaling activity is associated with the risk of type 2 diabetes, as well as other glycemic and obesity-related traits." (PMID 40858837, 2025). "Research related to the increase in CRP and IL-6 levels associated with obesity also validated the existence of immune cell infiltration in the obese population." (PMID 40612555, 2025). "Elevated IL-6 levels have been linked to obesity and insulin resistance and have been shown to play a role in macrovascular complications in patients with T2DM." (PMID 39901828, 2025). "Since obesity is associated with low-grade inflammation, we determined blood concentrations of IL-6 and TNF-α by ELISA." (PMID 40284173, 2025). "Obesity is also linked to subclinical chronic inflammation, characterised by the release of pro-inflammatory proteins into the circulation, including IL-6, TNF α, interleukin 8 (IL-8), and high-sensitivity C-reactive protein (C-RP hs)." (PMID 40310144, 2025). "Applying qRT-PCR, we also detected increase expression of the cytokines IL-6, IL-8, and TNFα, key players in the obesity-associated BC progression in tumors grown under ME conditions." (PMID 40868123, 2025).
Obesity (continued). "Previous studies using IL-6R cKO mice found that loss of IL-6 signal impaired Th1 and Th17 immune responses and reduced inflammation and diet-induced insulin resistance in the early stage of diet-induced obesity." (PMID 40936905, 2025). "Elevated concentrations of inflammatory markers, including C-reactive protein (CRP), interleukin-6 (IL-6), and tumor necrosis factor-alpha, have been consistently linked to cardiovascular disease, cancer, diabetes, obesity, and other metabolic disorders." (PMID 41228434, 2025). "To strengthen the translational relevance of our findings and emphasize the contribution of IL-6 signaling to the immune modulation of obesity-associated pancreatic injury, we employed an adoptive transfer model to validate our results." (PMID 40693271, 2025). "Other researchers have verified that chronic JAK-STAT3-SOCS3 signaling induced by leptin and IL-6 is implicated in obesity, cancer, and aging." (PMID 40149853, 2025). "In T2D, interleukins like IL-6 and IL-18 contribute to insulin resistance and the inflammatory environment associated with obesity." (PMID 40804870, 2025). "IL-6 has been linked also to obesity-related cardiac dysfunction, including impaired exercise capacity and elevated natriuretic peptides in HFpEF patients, even after adjusting for BMI." (PMID 41375727, 2025). "Elevated cytokines, such as TNF-α and IL-6, impair tissue recovery, while obesity-associated dyslipidemia amplifies ROS-induced cellular damage." (PMID 40282189, 2025). "Other inflammatory markers, such as tumor necrosis factor, interleukin-1, and interleukin-6, have also been shown to contribute to an increased risk of obesity." (PMID 40077689, 2025). "It is extensively documented that obesity is a condition of chronic low-grade inflammation associated with an increased secretion of adipokines, chemokines, and cytokines, including TNFa and IL-6, from AT." (PMID 40277905, 2025). "Obesity is associated with elevated levels of IL-6, TNF-α, CRP, and leptin, as well as altered macrophage profiles - all of which contribute to systemic and neural inflammation." (PMID 40909065, 2025). "This brings into focus the complex interplay between obesity and diabetes and markers such as leptin, IL6, TNFα, and IGFs in elevating the risk of endometrial cancer." (PMID 38339282, 2024). "Epicardial adipose tissue (EAT) is a rich local source of IL-6 signaling in obesity and a key contributor to a higher-risk of cardiac events in patients, and therefore likely contributes to cardiac tissue levels." (PMID 39063055, 2024). "For instance, obesity is associated with increased secretion of interleukin 6 (IL-6) and leptin and reduced secretion of adiponectin from AT." (PMID 39408921, 2024). "Obesity is associated with an increased IL-6 serum level, while there is a reduced IL-6 level in the central nervous system (CNS) in overweight and obese patients." (PMID 38474057, 2024). "Insulin resistance and adipocyte proliferation caused by obesity lead to the secretion of inflammatory mediators by adipocytes, such as Interleukin-6 (IL-6), Tumor Necrosis Factor-alpha (TNF-α), and C-reactive protein (CRP)." (PMID 38933362, 2024). "PDAC initiation and inflammation are closely related, as the risk factors for PDAC, such as smoking, diabetes, obesity, high-fat diet, and alcoholism, promote inflammatory signaling through the release of IL-6 and NF-κB." (PMID 38919953, 2024). "Regarding fetal predictors, in a cohort of children born extremely premature (< 28 weeks gestational age), showed that elevated IL-6 on day 1 in the newborn was associated with an increased risk for obesity at 2 years in multivariate models." (PMID 38800487, 2024). "IL-6, a pleiotropic inflammatory cytokine, is closely linked to obesity and functions as a “metabolic hormone”, influencing the homeostatic regulation of glucose, protein, and lipid metabolism." (PMID 39201638, 2024).
Obesity (continued). "It has been shown that inflammation associated with obesity can lead to a gradual increase in the risk of stroke, as increased IL-6 concentration in plasma is an important risk factor for CVD." (PMID 39200092, 2024). "Obesity, like diabetes, is associated with peripheral inflammation via multiple cytokine releases including IL-1, IL-6 and TNF-α28." (PMID 38290839, 2024). "On the other hand, one research work revealed IL-6 as an independent predictor of type 2 diabetes, not TNF, while another demonstrated that hsCRP is a more sensitive marker associated with obesity than IL-6 and TNF." (PMID 38396488, 2024). "Obesity is associated with autoimmunity through an increase in pro-inflammatory cytokines (IL-6, TNF alpha, and IL-17) and more than 50 adipokines as well as changes in the expression of the apoptotic inhibitor of macrophages." (PMID 38775508, 2024). "Other studies provide evidence of an association between obesity and some inflammatory markers, such as interleukin-6 (IL-6), C-reactive protein (CRP), and tumor necrosis factor-α (TNF-α)." (PMID 38634087, 2024). "A lower Shannon index has previously been associated with poor health status including obesity, inflammation (C-reactive protein, interleukin-6), sugary drinks, and diarrhea." (PMID 38924513, 2024). "STAT3 and SOCS3 play important roles in the downstream pathway of IL-6 and are associated with muscle atrophy in obesity and diabetes." (PMID 38561446, 2024). "The influence of genetic polymorphisms, including IL6 polymorphisms, on the increased risk of obesity and T2D was investigated." (PMID 38250713, 2024). "Among the evaluated cytokines, IL-6 has been widely associated with obesity and increased metabolic risk, which is reflected in our cohort with its positive correlation with BMI and negative correlation with phase angle." (PMID 38892006, 2024). "Elevated systemic pro-inflammatory markers like C-reactive protein, TNF-α, TGF-β, leptin, and IL-6 are linked to the obesity." (PMID 38762465, 2024). "MCP-1 and IL-6 were associated with overweight and obesity (p = 0.01–0.01–0.04, respectively); IL-6 and IL-8 were positively correlated with fat mass and CRP serum levels (p = 0.02–0.04, respectively)." (PMID 38892570, 2024). "In contrast to the reported obesity-associated leptin resistance, central IL-6 trans-signaling appears to be stimulated in obesity." (PMID 39723211, 2024). "Circulating TGF-β, IL- β and IL-6 levels also help clarify why asthma is positively associated with obesity, Type 2 diabetes, hypertension, and insulin resistance, whereas allergic rhinitis is negatively linked to these conditions." (PMID 38629073, 2024). "On the other hand, in adipocytes, IL-6 induces the release of FFAs and leptin and blunts obesity-associated metabolic complications." (PMID 38544694, 2024). "High levels of IL-6 are linked to chronic inflammatory diseases and conditions like obesity and metabolic syndrome." (PMID 39273314, 2024). "Despite the advantages of selectively investigating a role for IL-6 trans-signaling in obesity-linked VT, other cytokines are also likely involved." (PMID 39125976, 2024). "This knowledge offers new therapeutic opportunities for targeting PTP1B, IL6 or PML-loss induced SREBP signalling in the context of obesity." (PMID 38969865, 2024). "Obesity causes chronic, systemic inflammation, which is correlated with inflammatory markers (as in our study—IL-6)." (PMID 38786737, 2024). "Interleukin-6 (IL-6): IL-6 is a key inflammatory mediator, with elevated levels linked to autoimmune diseases, obesity, and chronic inflammatory conditions." (PMID 39683427, 2024). "Although the mechanism underlying obesity-related IL-6 upregulation is not fully understood, increase in IL-6 levels affect redox balance, mitochondrial physiology, and satellite cells in skeletal muscle." (PMID 39376657, 2024).